PARP1 (poly(ADP-ribose) polymerase 1)
Diseases named in the same sentence as PARP1 in open-access papers (continued):
Sharing a sentence is not in itself a finding about the gene and the disease.
cervical carcinoma (continued). "Further differential analysis of the PARP1 and HMGB1 genes revealed that PARP1 showed high expression in both the cervical cancer chip GSE9750 and the TCGA-CESC dataset, while HMGB1 only exhibited high expression in the cervical cancer chip GSE9750." (PMID 37773127, 2023). "For example, STAT1 can affect the development of cervical cancer by regulating the expression of PARP1." (PMID 36911390, 2023). "Combination treatment with PARP1-i enhances both standard treatment options IR + cDDP and IR + HT in cervical cancer cell lines." (PMID 33926008, 2021). "Both radiosensitizers, cDDP and HT are effective when combined with IR, but this effect on the cervical cancer cells is enhanced when PARP1-i was added as well." (PMID 33926008, 2021). "By looking into the surviving fractions and DNA double strand breaks, our results suggest that PARP1-i sensitizes cervical cancer cells for the conventional therapies." (PMID 33926008, 2021). "This was studied in cervical cancer cell lines (SiHa, HeLa, C33A and CaSki) treated with hyperthermia (42 °C) ± ionizing radiation (2–6 Gy) ± cisplatin (0.3–0.5 μM) ± PARP1-inhibitor (olaparib, 4.0–5.0 μM)." (PMID 33926008, 2021). "The radiobiological response to IR, cDDP, HT, PARP1-i and combinations in human cervical cancer cell lines vary per treatment and cell line." (PMID 33926008, 2021). "The functional effects of MAPK4 knockout on the sensitivity of cervical cancer to radiation treatment and PARP1 inhibitors were further examined using xenograft tumor mouse models in vivo." (PMID 32711558, 2020). "Collectively, our data suggest that combined application of MAPK4 knockout and radiation treatment or PARP1 inhibition can be used as therapeutic strategy for advanced cervical carcinoma." (PMID 32711558, 2020). "MAPK4 is further found to affect the sensitivity of cervical cancer cells to PARP1 inhibitors by activating AKT phosphorylation." (PMID 32711558, 2020). "Given that MAPK4 deletion enhanced the sensitivity of cervical cancer cells to radiation and PARP1 inhibitors, we next investigated the effect of MAPK4 deletion in vivo." (PMID 32711558, 2020). "Collectively, our data suggest that combined application of MAPK4 knockout and PARP1 inhibition can be used as therapeutic strategy in radiation treatment for advanced cervical carcinoma." (PMID 32711558, 2020). "Drug-sensitivity of cervical cancer cells to PARP1 inhibitors, olaparib or veliparib, was analyzed by CCK-8 cell viability assays, and the 50% inhibitory concentration (IC50) was quantified using GraphPad Prism." (PMID 32711558, 2020). "miR-7-5p was demonstrated to negatively regulate PARP-1 protein and gene expression in cisplatin-resistant cervical cancer cells, and facilitates DNA repair and maintain cell survival." (PMID 32711558, 2020). "In conclusion, our data provides experimental evidence on the contribution of PARP-1 inhibition in enhancing the cytotoxicity of CDDP in cervical cancer cells." (PMID 31303961, 2019). "With regard to PARP1, our findings are consistent with previous data showing that PARP1 levels post IR are inversely correlated to radiation sensitivity in cervical cancer cells." (PMID 31242951, 2019). "We found that the transcriptional repression of mortalin by Mortaparib caused inactivation of PARP1 leading to accumulation of DSB (Double-Strand Breaks) and apoptosis in cervical cancer cells." (PMID 31856867, 2019). "In terms of the obtained results, the hub proteins KAT2B, PARP1, CDK1, GSK3B, WNK1, and CRYAB have been associated with several cancers in previous studies, but their association with cervical cancer is proposed here for the first time." (PMID 30020984, 2018).
cervical carcinoma (continued). "Our expression profile data of PARP1 demonstrates significantly increased expression in primary cervical cancer tissue biopsies and CC cell lines." (PMID 28993682, 2017). "So, our data implicates that better anti-metastatic effect can be obtained for cervical cancer cells when PARP-1 inhibition is combined with carbon ion exposure." (PMID 27659937, 2016). "Two-fold overexpression of PARP-1 protein has been shown in cervical cancers as compared to normal uterine cervix cells." (PMID 23396107, 2013). "PARP-1 Ala762Ala(GCG/GCG) carriers in patients with cervical carcinoma were significantly higher than those in controls (OR: 2.70, 95% CI: 1.47–3.70; P<0.001)." (PMID 22624032, 2012). "In summary, our study firstly shows a significant association between the PARP-1 Ala762Ala(GCG/GCG) genotype and increased risk of cervical carcinoma." (PMID 22624032, 2012). "Our findings demonstrate that cepharanthine significantly induces mitochondrial apoptosis in human cervical cancer cells both in vitro and in vivo, as evidenced by the increased expression of cleaved PARP-1 and cleaved caspase-3 proteins, along with an elevated Bax/Bcl-2 ratio." (PMID 41300481, 2025). "It should be noted that the bioinformatics analysis conducted in the present study predicted that CpG-ODNs might regulate the downstream targets poly ADP-ribose) polymerase 1 (PARP1)/X-ray repair cross complementing 1 (XRCC1) in RKI in cervical cancer." (PMID 37773127, 2023). "Herein, we set out to investigate the role of CpG-ODNs in RKI in cervical cancer and our results found that CpG-ODNs could inactivate the PARP1/XRCC1 axis to prevent RKI in cervical cancer." (PMID 37773127, 2023). "CpG-ODNs may mitigate cervical cancer RKI by blocking the activation of the PARP1/XRCC1 signaling axis, inhibiting DNA damage and oxidative stress response in renal tubule epithelial cells." (PMID 37773127, 2023). "To conclude, the present study provide evidence indicating that CpG-ODNs may attenuate RKI in cervical cancer by blocking PARP1/XRCC1 axis activation and inhibiting DNA damage and oxidative stress in renal tubular epithelial cells." (PMID 37773127, 2023). "Here, we demonstrated a critical role for IFN-γ/STAT1/STAT3 signaling in regulating PARP1 levels in HGSOC cells, in line with our recent results in cervical cancer, and with the emerging evidence on the functional interplay between the STATs signaling cascade and PARP1." (PMID 37190289, 2023). "Therefore, this research focusses on the targeting drug PARP1-i, which shows promising results on the cellular level and is clinically available against cervical cancer." (PMID 33926008, 2021). "Besides PARP1-i, there are other targeted drugs under investigation in order to sensitize cervical cancer cells to cisplatin." (PMID 33926008, 2021). "In addition, high PARylation activity is correlated with sensitivity to olaparib in cervical cancer cells, and represents a biomarker for the identification of patients likely to benefit from PARP1 inhibition." (PMID 32711558, 2020). "Moreover, MAPK4 knockout enhanced the sensitivity of cervical cancer to radiation and PARP1 inhibitors in mouse xenograft models." (PMID 32711558, 2020). "Together, these findings demonstrated that MAPK4 knockout could inhibit DNA repair and improve the sensitivity of cervical cancer to irradiation treatment and PARP1 inhibitors in vivo." (PMID 32711558, 2020). "Together, these results demonstrated that MAPK4 knockout alongside with PARP1 inhibition may improve the therapy of cervical cancer." (PMID 32711558, 2020). "Thus, we then investigated the effect of MAPK4 knockout on the sensitivity of cervical cancer cells to PARP1 inhibitors, olaparib or veliparib." (PMID 32711558, 2020). "Furthermore, the IC50 of PARP1 inhibitors was detected by re-expressing MAPK4 or over-expressing CA-AKT in MAPK4 knockout cervical cancer cells." (PMID 32711558, 2020).
cervical carcinoma (continued). "Moreover, in vivo results demonstrated that MAPK4 knockout enhanced the sensitivity of cervical cancer to radiation and PARP1 inhibitors in mouse xenograft models." (PMID 32711558, 2020). "Furthermore, MAPK4 knockout was found to affect the sensitivity of cervical cancer cells to poly ADP-ribose polymerase 1 (PARP1) inhibitors by activating the phosphorylation of AKT." (PMID 32711558, 2020). "In this study, we have not only demonstrated the suppressive role of MAPK4 knockout on AKT phosphorylation, but also identified the relationship between MAPK4 knockout and enhanced sensitivity of cervical cancer to radiation treatment and PARP1 inhibitors in cells and mouse models." (PMID 32711558, 2020). "Because MAPK4 expression is associated with patient survival, these result suggest that MAPK4 may serve as a potential synergetic therapeutic target with PARP1 inhibitors in radiotherapy of cervical cancer." (PMID 32711558, 2020). "However, the synergistic role of PARP1 inhibition in combination with MAPK4 intervention for cervical cancer therapy is yet to be elucidated." (PMID 32711558, 2020). "In addition, MAPK4 knockout enhanced the sensitivity of cervical cancer cells to PARP1 inhibitors, olaparib and veliparib." (PMID 32711558, 2020). "An association between poly ADP-ribose polymerase 1 (PARP1) Val762Ala polymorphism (rs1136410) and cancer therapy response has been identified, and PARP1 genotypes have been proposed to be an independent prognostic factor in cervical cancer." (PMID 32711558, 2020). "In conclusion, PARP-1 inhibition might augment cisplatin cytotoxicity in cervical cancer cells by modulating β-catenin signaling pathway." (PMID 31303961, 2019). "We hypothesized that PARP-1 inhibition might improve the sensitivity of cervical cancer cells to cisplatin by diminishing DNA repair." (PMID 31303961, 2019). "In addition, it has been demonstrated that PARP1 also controls the expression of RAD51, a protein already associated with chemo-radioresistance in cervical cancer." (PMID 31242951, 2019). "In this study, we examined whether pharmacological or genetic abrogation of PARP-1 could confer enhanced CDDP sensitivity in two cervical cancer cell lines, HeLa (HPV 18 positive, adenocarcinoma) and SiHa (HPV 16 positive, squamous cell carcinoma)." (PMID 31303961, 2019). "In addition, a recent study has showed that alteration of PARP-1 at residue A762A significantly depresses PARP-1 activity and is related to increased risk of cervical cancer." (PMID 24877058, 2014). "Our findings suggest that PARP-1 dysfunction may play an important role in the development of cervical carcinoma." (PMID 22624032, 2012). "Therefore, in the current population-based case-control study, we investigated the genotype distributions of the PARP-1 Val762Ala(GTG/GCG) in patients with cervical carcinoma or CIN." (PMID 22624032, 2012). "In addition, to investigate whether CpG-ODNs attenuate RKI in cervical cancer by regulating PARP1, we examined the expression of PARP1 in the kidney tissues of RKI mice treated with two CpG-ODNs (CpG-ODN2006 and CpG-ODN2216)." (PMID 37773127, 2023). "In addition, it has been shown that PARP-1 inhibition may augment cisplatin cytotoxicity in cervical cancer cells by diminishing DNA repair and suppressing β-catenin signaling pathway." (PMID 32711558, 2020). "Therefore, combining a low dose of cDDP with HT and a PARP1-i may be a promising approach to increase tumor control whilst reducing systematic cDDP-toxicity, particularly in women with (recurrent) cervical cancer." (PMID 27557507, 2017). "We recently demonstrated that, in cervical cancer cells, STAT1 (Signal Transducer and Activator of Transcription) controls PARP1 levels, also interacting with STAT3." (PMID 37190289, 2023). "In a set of pre-treatment samples from 117 cervical cancer patients treated with CRT, the proteins ATM, PARP-1, DNA-PKcs, Ku70 and Ku86 were quantified using fluorescence immunohistochemistry." (PMID 34830902, 2021).
cervical carcinoma (continued). "Additionally, we observed that the treatment with PTX + CIS increased PARP-1 cleavage in SiHaP and SiHaCIS-R cells, which potentiates the apoptotic effects of these drugs, due to that these mechanisms are involved in the induction of apoptosis in human cervical cancer cells." (PMID 33680921, 2020). "We found that MAPK4-knockout cervical cancer cells showed lower AKT phosphorylation level, and had heightened sensitivity to radiation treatment and PARP1 inhibitors." (PMID 32711558, 2020). "In this study, we have investigated the combined effect of PARP-1 inhibition and CDDP on cell proliferation, survival, apoptosis, and invasion and migration in cervical cancer." (PMID 31303961, 2019). "Notably, we recently demonstrated that, in cervical cancer cells, STAT1 controls PARP1 levels through multiple mechanisms, possibly involving also STAT3." (PMID 37190289, 2023). "Given other neuroendocrine carcinomas and other types of cervical cancer have been proved to have expression of programmed cell death protein 1 ligand 1(PD‐L1) and poly ADP‐ribose polymerase‐1(PARP1), we would measure and analyze these proteins in this invasive cancer." (PMID 34076351, 2021). "The cleaved forms of PARP-1 were elevated in RAME-treated cervical cancer cells, which did not increase by RAME in S6K1-deficient cells." (PMID 31387554, 2019). "In addition to this, we provide additional evidence concerning the beginning of the DDR pathway in CSC from cervical cancer, where ATM, H2A.X, and PARP1 are key elements involved in the detection of DNA damage." (PMID 31073313, 2019). "The frequency of the PARP-1 Ala762Ala(GCG/GCG),Val762Ala(GTG/GCG) and Val762Val(GTG/GTG) genotypes were 8.5%, 59.4% and 32.1%, respectively in controls, 19.3%, 52.5% and 28.2% in patients with cervical carcinoma." (PMID 22624032, 2012). "However, if cervical cancer cells were co-infected with a lentivirus of MCPIP1 and XIAP, XIAP overexpression could attenuate the increase in cleaved caspase-3 and cleaved PARP1 protein activated by MCPIP1 overexpression." (PMID 39408613, 2024). "Furthermore, our Western blot analysis showed that the protein level of pro-caspase-3 decreased, but cleaved caspase-3 and cleaved PARP1 increased in MCPIP1-overexpressing HeLa and SiHa cells, which further validated the pro-apoptotic role of MCPIP1 in cervical cancer cells." (PMID 39408613, 2024). "Therefore, we speculate that PARP1 may be a potential target for CpG-ODNs in the treatment of RKI in cervical cancer, and CpG-ODNs may alleviate RKI in cervical cancer by downregulating PARP1 expression." (PMID 37773127, 2023). "Furthermore, the KAT2B, PARP1, CDK1, GSK3B, WNK1, and CRYAB, proteins are associated with various cancer types, but their roles in cervical cancer have not been identified." (PMID 30020984, 2018). "Chromatid scattering was observed in cervical cancer cells with increased PARP1 and PARP2 protein levels (HeLa, C33-A), suggesting that PARP1 and PARP2 protein levels could be used as a predictive biomarker for the efficiency of olaparib treatment, as previously proposed." (PMID 29262611, 2017). "We recently demonstrated that in cervical cancer cells (HPV-positive CaSki and C-4I), a perturbation in the balanced expression/activation of STAT1 and STAT3 might improve the efficacy of DNA-damaging treatments, at least partially, by lowering PARP1 levels in tumors." (PMID 37190289, 2023).
triple-negative breast carcinoma (40 papers, 2011 to 2025). An invasive breast carcinoma which is negative for expression of estrogen receptor (ER), progesterone receptor (PR), and human epidermal growth factor receptor 2 (HER2). "It is reported that the PARP1 inhibitor Olaparib can promotes the binding of the transcription factor nuclear phosphoprotein (NPM1) to the PD-L1 promoter in triple-negative breast cancer cells,thereby activating PD-L1 transcription." (PMID 40406122, 2025). "Our group showed metformin and oxamate plus doxorubicin-induced late apoptosis, an increase of protein caspase-3, and a drop in PARP-1 in triple-negative breast cancer cells." (PMID 37223676, 2023). "We have demonstrated that three different PARPis are known to target the PARP1/2 activity, olaparib, talazoparib, and veliparib, impair the VM formation of triple negative breast cancer cells, independently of the BRCA1/2 status." (PMID 36555812, 2022). "PARP-1 (nuclear) expression and BRCA1 mutations were mainly detected in triple negative breast cancer patients, and the latter were correlated with decreased survival." (PMID 35406503, 2022). "PARP1 inhibitors (PARPi) are currently approved for BRCAmut metastatic breast cancer, but they have shown limited response in triple negative breast cancer (TNBC) patients." (PMID 35008392, 2022). "EGFR is another kinase that phosphorylates PARP1, and the inhibition of both EGFR and PARP1 results in synthetic lethality in highly aggressive triple negative breast cancers (TNBCs)." (PMID 34639169, 2021). "Randomized phase II study has shown adding PARP-1 inhibitor BSI-201 to cytotoxic chemotherapy improves clinical outcome in patients with triple-negative breast cancer." (PMID 21504625, 2011). "PARP1 is a base excision repair protein that could promote cancer cell survival, and is an effective target in triple-negative breast cancer." (PMID 33246450, 2020). "Low miR-221-3p expression may lead to the poor prognosis of triple-negative breast cancer patients through regulating PARP1." (PMID 30891072, 2019). "Targeted PARP1 inhibition has proven especially effective as a treatment for patients carrying a BRCA1 mutation, and in triple-negative breast cancer (because of the similarities with BRCA1-mutated tumors) leading to an inhibition of dual DNA repair pathways leading to cell death." (PMID 27357824, 2016). "Furthermore, PARP-1 inhibitors are considered as an effective clinical complement to chemotherapy, notably in triple-negative breast cancer." (PMID 23405229, 2013). "A study of triple-negative breast cancer cells with mBRCA1 showed that targeting PARP1 using the CRISPR/Cas9 system could increase sensitivity to chemotherapy drugs, including doxorubicin, gemcitabine, and docetaxel, and a lower dose of these drugs is required to achieve therapeutic efficacy." (PMID 35715750, 2022). "In triple negative breast cancer, DAXX protein can trigger Caspase-3 which prompts apoptosis by cleaving PARP-1 protein." (PMID 41357233, 2025). "The HR-/HER2- group, as the triple-negative breast cancer type, was considered resistant to CDK4/6i with higher ‘‘p-YB-1/PARP1’’ expression." (PMID 38037159, 2023). "Nonetheless, prior research has indicated that XRCC1 deficiency can lead to PARP1 hyperactivation, and notably, lack of XRCC1 expression has been reported in tumours, including triple-negative breast cancers." (PMID 41459749, 2025). "The PARP1 inhibitor olaparib combines well with DNA damaging treatments and other chemotherapies and shows combination effects with selinexor in triple negative breast cancers cells independent of BRCA1 status." (PMID 28467801, 2017).